FHL1 (four and a half LIM domains 1)
Description:
May have an involvement in muscle development or hypertrophy.
Synonyms: FHL-1; SLIM; SLIM-1; SLIM1; KYO-T; bA535K18.1; FHL1B; XMPMA; FLH1A; MGC111107; FCMSU; FHL1A; KYOT; RBMX1A; RBMX1B; SLIMMER
Tractability: Antibody: its Gene Ontology location is reachable by antibodies, with high confidence. PROTAC: UniProt records ubiquitination sites on it; ubiquitination databases record sites on it; its protein half-life has been measured.
Gene: Protein-coding gene on chromosome X (136,146,702 to 136,211,359, forward strand). Ensembl gene ENSG00000022267.
Subcellular location: Cytoplasm (Isoform 1); Cytoplasm (Isoform 3); Nucleus; Nucleus (Isoform 2); Cytoplasm, cytosol
Subcellular location (Human Protein Atlas): Cytosol; Plasma membrane
Gene Ontology:
Molecular function: channel activator activity; potassium channel activator activity; protein binding; transmembrane transporter binding
Biological process: negative regulation of cell growth; negative regulation of G1/S transition of mitotic cell cycle; negative regulation of G2/M transition of mitotic cell cycle; positive regulation of potassium ion transmembrane transport; regulation of atrial cardiac muscle cell membrane depolarization; animal organ morphogenesis; muscle organ development
Cellular component: cytoplasm; focal adhesion; nucleus; plasma membrane; cytosol
Homologues: Orthologues: mouse Fhl1 (95% identical), macaque FHL1 (86% identical), dog FHL1 (84% identical), pig FHL1 (83% identical), rabbit FHL1 (82% identical), guinea pig Fhl1 (79% identical), tropical clawed frog fhl1 (78% identical), rat Fhl4 (69% identical), zebrafish fhl1a (68% identical), mouse Fhl4 (67% identical), zebrafish fhl1b (57% identical). Paralogues in human: ZFHX4 (28% identical), ZFHX3 (27% identical), ZFHX2 (22% identical), LMX1A (19% identical), LHX8 (18% identical), LMX1B (18% identical), LHX4 (18% identical), LHX6 (18% identical), LHX9 (17% identical), LHX3 (17% identical), LHX1 (17% identical), LHX5 (17% identical), and 8 more.
Diseases named in the same sentence as FHL1 in open-access papers:
FHL1 is named in the same sentence as 144 diseases in open-access papers, as found by Europe PMC text mining. Sharing a sentence is not in itself a finding about the gene and the disease. The quoted sentences say what the papers report.
cardiac hypertrophy (21 papers, 2014 to 2025). "Further segregation studies revealed that his 50-year-old mother and 81-year-old grandmother were heterozygous carriers of the FHL1 variant, both with mild signs of cardiac hypertrophy and diastolic dysfunction." (PMID 32659924, 2020). "Studies from our laboratory have reported FHL1 as a novel ERK associated MAPK scaffold protein that mediates MAPK/ERK signaling responses at the sarcomere during stress-induced cardiac hypertrophy." (PMID 26973524, 2016). "FHL-1 is assumed to activate GDF8 in SKM but is also associated with myocardial hypertrophy." (PMID 40649974, 2025). "Thus, the reversion of diastolic dysfunction and cardiac atrophy in N2B-KO mice by reduced expression of functional RBM20 is dependent on titin’s mechanical properties and associated with a posttranscriptional effect on FHL1, which links titin-based biomechanics to cardiac hypertrophy signaling." (PMID 27889803, 2016). "Previous studies on FHL1 have shown that its mutation leads to abnormal muscle development, and the expression of FHL1 is upregulated in pathological myocardial hypertrophy and cardiomyopathy 17-19." (PMID 34335951, 2021). "JMJD2A and JMJD3 were reported to regulate cardiac hypertrophy by epigenetically targeting the FHL1 (four-and-a-half LIM domains 1) and the β-MHC promoter, respectively." (PMID 32625104, 2020). "For instance, JMJD2A promotes cardiac hypertrophy in response to hypertrophic stimuli in mice through binding to the FHL1 promoter, upregulating FHL1 expression, and downregulating H3K9 trimethylation." (PMID 32461996, 2020). "JMJD2A and JMJD3 were reported to regulate cardiac hypertrophy by epigenetically targeting FHL1 and MHC promoter, respectively." (PMID 32625104, 2020). "Loss of function studies highlighted that both proteins, FHL1 and ANKRD1, have detrimental roles in Gαq and phenylephrine-induced cardiac hypertrophy." (PMID 31052420, 2019). "However, FHL1 is significantly increased in cardiac failure, cardiac hypertrophy, pulmonary hypertension, and arrhythmias." (PMID 35268023, 2022). "FHL1 was also found to be upregulated in a titin PEVK knockout mouse model that developed cardiac hypertrophy and increased passive tension, strengthening the importance for an interaction between titin’s molecular spring elements and FHL1 during regulation of LV passive/diastolic tension." (PMID 34745373, 2021). "Additionally, changes indicative of cardiac hypertrophy and heart failure, e.g. Fhl1 upregualtion and Fhl2 downregulation, Carp induction) and upregulation of β-myosin heavy chain were observed at the protein level in the myocardium of KI/KI mice." (PMID 30048712, 2018). "Both FHL1 and FHL2 have not only been linked to cardiac hypertrophy signaling but also bind titin." (PMID 27889803, 2016). "However, under conditions of pressure overload, adult Fhl1-/- hearts displayed a blunted response to cardiac hypertrophy." (PMID 26973524, 2016). "FHL1 (four-and-a-half LIM domains senses biomechanical stress and promotes cardiac hypertrophy by affecting the MAPK signaling cascade." (PMID 34540911, 2021). "More molecular studies confirmed that empagliflozin ameliorates the expression of cardiac hypertrophy markers such as actin alpha (ACTA1), four-and-a-half LIM domains 1 (FHL1), myosin light chain 2a (MLC2A) in high-glucose-exposed human-induced pluripotent stem cells-derived cardiomyocytes." (PMID 36552708, 2022). "FHL1 directly interacts with RAF-MEK-ERK to physically insulate the MAPK pathway to the titin N2B region of the sarcomere in a Gq stimulus-specific manner and efficiently transmit MAPK signals to regulate cardiac hypertrophy." (PMID 31052420, 2019). "For example, in comparison with their wild-type littermates, fhl1−/− mice have been reported to develop diminished cardiac hypertrophy following TAC (transverse aortic constriction) or cardiac-specific Gαq overexpression, suggesting a pro-hypertrophic role for FHL1." (PMID 24219103, 2014).
cardiac hypertrophy (continued). "Four-and-a-half LIM domain 1 (FHL1) is a key component of the mechano-transducer machinery in the heart, and KDM4A can occupy the FHL1 promoter in response to transverse aortic constriction and up-regulate FHL1 levels by removing methyl groups from H3K9me3 during cardiac hypertrophy." (PMID 37692513, 2023). "A plausible interpretation of such data is that PKD1 regulates cardiac hypertrophy through a mechanism that is independent of its kinase activity, in which case FHL1- and FHL2-mediated regulation of neurohormonal PKD activation would be more likely to regulate other PKD-mediated functions." (PMID 24219103, 2014). "Thus the roles that FHL1 and FHL2 play in regulating cardiac hypertrophy in the in vivo setting may be isoform-specific and dependent on the nature of the stress stimulus that triggers the hypertrophic response." (PMID 24219103, 2014). "Interestingly, at least in some settings, FHL1 and FHL2 appear to have differential effects on cardiac myocyte ERK activity, raising the possibility that the ERK pathway may be critical in mediating the regulation of cardiac hypertrophy by FHL proteins." (PMID 24219103, 2014).
breast carcinoma (17 papers, 2005 to 2025). "In a Kaplan-Meier survival analysis, higher FHL1 expression in tumors of breast cancer patients that had received radiotherapy was associated with poorer disease-free survival (DFS) and OS." (PMID 32587768, 2020). "The collective findings established an association between the effects of FHL1 on the estrogen signaling pathway and breast cancer cell growth." (PMID 32587768, 2020). "Simultaneously, the differentially expressed genes related to breast cancer, such as FHL1, GPM6B, RELN, and CXCL10 were discovered between the two risk groups." (PMID 38748500, 2024). "Studies existed that silencing FHL1 noticeably fosters the growth of cervical cancer cells, and decreased FHL1 also hastens the growth of breast cancer cells, indicating that FHL1 exerted an inhibitory effect in several cancers." (PMID 36017148, 2022). "Previous studies have shown that FHL1 binds the oestrogen receptor transcription factor to regulate breast cancer cell growth and that the binding of FHL2 to the transcription factor E4F1 inhibits its transcriptional regulation and promotes cell proliferation." (PMID 36418297, 2022). "Another report suggests that FHL1 suppresses the transcriptional activity of ERα in human breast cancer cells through regulation of AKT58." (PMID 32587768, 2020). "Several of them like CCL22, four and a half LIM domains protein 1 (FHL1) and leukemia inhibiting factor (LIF) were detected in the breast CAAT proteome and have been linked with breast cancer proliferation and growth." (PMID 28525384, 2017). "Downregulation of FHL1 promoted the growth of human lung cancer cells, hepatoma cells, and breast cancer cells and reduced EMT in breast adenocarcinoma cells." (PMID 26908444, 2016). "FHL1 expression is suppressed in a variety of tumors including lung cancer, breast cancer, brain tumors, and gastric cancer." (PMID 24952875, 2014). "FHL1 as a tumor repressor gene is authenticated to be poorly expressed in varying cancers, containing liver cancer, oral cancer, head and neck squamous cell carcinoma, and breast cancer." (PMID 36017148, 2022). "FHL1 inhibits both anchorage-dependent and -independent breast cancer cell growth, which could be mediated by physical and functional interactions with estrogen receptors (ER) and modulation of transcriptional activities of ERα and ERβ." (PMID 32587768, 2020). "Similarly, FHL1 appears to play a suppressive role in breast cancer through interactions with multiple signaling pathways." (PMID 32587768, 2020). "Moreover, in breast cancer patients, high FHL1 expression positively correlated with cytoplasmic CDC25C accumulation and negatively correlated with nuclear CDC25C accumulation." (PMID 28094252, 2017). "FHL1 has been identified as a suppressor gene for a variety of malignant tumors and exerts antitumor effects by inhibiting tumor differentiation, proliferation, invasion, and metastasis, and low FHL1 expression is closely related to the invasion and metastasis of breast cancer." (PMID 37024893, 2023). "FHL1 induced the expression of tumor suppressor genes by increasing the nuclear translocation of Smad4 in hepatocellular carcinoma cells and inhibiting the phosphorylation of AKT in human breast cancer cells." (PMID 33322515, 2020). "Immunohistochemistry analysis revealed the absence of FHL1 expression in astrocitoma, breast carcinoma, renal carcinoma, hepatocarcinoma, pulmonary adenocarcinoma, prosthatic carcinoma and melanoma tumor samples compared to their corresponding normal tissues." (PMID 29454310, 2018). "In contrast, for breast cancer patients who were not treated with radiotherapy, FHL1 failed to be an independent poor prognostic factor of DFS and OS, although nodal status, grade, oestrogen receptor (ER) and HER2 were independent prognostic factors." (PMID 28094252, 2017).
breast carcinoma (continued). "In addition, two classifier genes were identified (FHL1 and CLDN5) highly discriminative between most "normal" tissue samples and all breast cancer samples analyzed." (PMID 16091131, 2005). "Using an engineered metastatic niche, we identified a 9‐gene signature (Dhx9, Dusp12, Fhl1, Ifitm1, Ndufs1, Pja2, Slc1a3, Soga1, Spon2) that successfully delineated metastatic breast cancer from nonmetastatic breast cancers including an invasive cell line without metastatic potential." (PMID 38193115, 2024). "Kaplan–Meier survival analysis showed that, for breast cancer patients who received radiotherapy, those with tumours that highly expressed FHL1 revealed significantly poorer DFS and OS than those with tumours with low FHL1 expression (DFS: P=2.814 × 10−5; OS: P=2.405 × 10−4)." (PMID 28094252, 2017).
cardiomyopathy (15 papers, 2014 to 2026). A disease of the heart muscle or myocardium proper. "Loss of FHL1 is advantageous in cardiomyopathy caused by Gαq overexpression, but deleterious in the MHC403/+ model of hypertrophic cardiomyopathy." (PMID 34745373, 2021). "FHL1 is also upregulated in mouse models of cardiomyopathy induced by myosin heavy chain missense mutations (MHC403/+), MLP deletion, in Gαq and Gsα transgenic mice as well as mice that overexpress β-adrenergic receptors." (PMID 34745373, 2021). "Mutations in the FHL1 gene, along with deletion of the FHL1 protein, are associated with rare hereditary myopathies and cardiomyopathies." (PMID 30083183, 2018). "Mutations in the FHL1 gene, and FHL1 protein deletion, are associated with rare hereditary myopathies and cardiomyopathies." (PMID 30083183, 2018). "Similarly, Fhl1, linked to cardiomyopathy and muscle metabolism, gained significance (Padj = 0.477 to 5.27e-04), potentially connecting α1A-AR’s anti-glycolytic function to Fhl1 activity." (PMID 40705823, 2025). "Loss of FHL1 in Gαq transgenic mice has been demonstrated to rescue the cardiomyopathy phenotype." (PMID 34745373, 2021). "Thus far, a number of FHL1 mutations have been identified, resulting in at least six different X-linked myopathies or cardiomyopathies." (PMID 30083183, 2018). "Carriers of FHL1 and SCN5A variants face an increased risk of developing cardiomyopathies and arrhythmias." (PMID 41287789, 2025). "It has been suggested that the subtype of cardiomyopathy is determined by the variant type and site location as seen for other cardiomyopathy-associated genes (e.g., DES, LDB3, BAG3, FHL1)." (PMID 33802723, 2021). "Collectively, the JAK-STAT pathway may signal to reduce the transcriptional activity of EP300 (i.e., increased T887 phosphorylation) and the expression of FHL1/SLIM, which is implicated in protein turnover and cardiomyopathy." (PMID 38389037, 2024). "However, in α-myosin heavy chain R403Q missense mutation mice (MHC403/+), another mouse model for hypertrophic cardiomyopathy with elevated levels of FHL1, ablation of the gene had opposing effects and exacerbated the cardiomyopathy phenotype." (PMID 34745373, 2021). "Fhl1 ablation exacerbated the cardiomyopathy in hypertrophic cardiomyopathy (HCM) mice." (PMID 26845333, 2016). "The magnitude of these physiological changes was accompanied in both HD models by reactivation of a foetal gene programme, including the up-regulation of Anp, Bnp, Fhl1 and Fhl2 and a reduction in the α- and β- isoforms of the myosin heavy chain, all typical markers of an induced cardiomyopathy." (PMID 25101683, 2014). "Recent studies have indicated that mutations in four and-a-half LIM domain protein 1 (FHL1) are associated with rare hereditary myopathies, including reducing body myopathy (RBM), X-Linked myopathy with postural muscle atrophy (XMPMA), Emery-Dreifuss muscular dystrophy (EDMD), and cardiomyopathies." (PMID 30083183, 2018). "Summarily, these studies provide clinical relevance for the function of the FHL1/PP5/Mapk-containing signalosome for N2Bus3 phosphorylation and the development of human cardiomyopathy." (PMID 34745373, 2021). "FHL1 exhibits baseline expression levels in many tissues and becomes specifically upregulated in the heart of many cardiomyopathy models, including MHC403+/ mice, MLP knockouts, Gαq and Gsα transgenic mice, as well as in cardiomyopathy patients." (PMID 34745373, 2021). "In fact, during the enrollment period of this study new genes that were not included in the cardiomyopathy panels used, such as FLNC or FHL1, have been associated with HCM." (PMID 28771489, 2017). "In addition to the expression of truncated or poisonous forms of FHL-1, the levels of FHL-1 are also altered in cardiomyopathies." (PMID 25961035, 2015).
lung carcinoma (14 papers, 2010 to 2025). "Studies have shown that FHL1 is downregulated in a variety of cancers, such as gastric cancer, lung cancer and oral cancer 8-10." (PMID 34335951, 2021). "For instance, FHL1 has been shown to inhibit both anchorage-dependent and -independent growth of human lung cancer cells via cell cycle arrest." (PMID 32587768, 2020). "The effects of different nutants of FHL1 on lung cancer cell proliferation were additionally investigated." (PMID 32587768, 2020). "Previously, it was indicated that LAYN, CCT4, CTHRC1, and FHL1 gene were correlated with the migrational potential of lung cancer cells." (PMID 27586393, 2016). "In agreement with previous reports, clear downregulation in the expression of the FHL1 gene was detected in lung cancer specimens." (PMID 20525254, 2010). "The four genes with lung cancer-associated alternative splice forms newly identified in this study were: CEACAM1, FHL1, MLPH, and SUSD2." (PMID 20525254, 2010). "In one study, FHL1 expression was shown to be downregulated in over 90 % of lung cancer patients." (PMID 41439026, 2025). "Moreover, overexpression of FHL1 resulted in a dramatic suppression in the growth of A549 lung cancer cells in nude mice." (PMID 41439026, 2025). "The inhibitory effect of FHL1 on lung cancer cell growth has been reported in vivo and in vitro." (PMID 36752296, 2023). "FHL1 promoted cell cycle arrest at both G1 and G2/M in lung cancer cells, thus regulating G1 and G2/M phase-related proteins, including significant inhibition of cyclin A, cyclin B1, and cyclin D, as well as upregulation of the cyclin dependent kinase inhibitors, p21 and p2759." (PMID 32587768, 2020). "Furthermore, FHL1 suppressed the levels of G1 and G2/M phase-related proteins, including cyclin A, B1, D, and E, resulting in G1 and G2/M cell cycle arrest in lung cancer cells." (PMID 33322515, 2020). "Importantly, lung cancer cells demonstrate a high level of resistance to complement-mediated lysis via activation of the classical pathway, as well as via the alternative pathway due to the role of CFH and FHL-1." (PMID 30987235, 2019).